BMI1 (BMI1 proto-oncogene, polycomb ring finger)
Diseases named in the same sentence as BMI1 in open-access papers (continued):
Sharing a sentence is not in itself a finding about the gene and the disease.
head and neck cancer (continued). "Bmi1 maintains the self-renewal of both normal and malignant human mammary stem cells, suppresses E-cadherin, and enhances stemness in head and neck cancer cells." (PMID 26023734, 2015). "Bmi1 is regulated by Twist1 which is one of the epithelial mesenchymal transition inducers in head and neck cancer cells." (PMID 24312366, 2013). "Therefore, elucidating therapeutic approaches targeting Bmi-1 can be leveraged to further research analysis to advance clinical treatment strategies for head and neck cancer." (PMID 39866230, 2025). "Thus, more elaborate studies are needed to determine the relevance of Bmi-1 expression in head and neck cancer, especially in relation to HPV status and disease progression." (PMID 36726797, 2023). "This review attempted to synthesize the current evidence on Bmi-1 within the context of head and neck cancer stem cells, and to provide support for future research aimed at targeting this master regulator of cancer cell stemness using novel therapeutic approaches." (PMID 36726797, 2023). "Due to the high rate of metastasis and recurrence observed in head and neck cancer, these findings render the role of Bmi-1 particularly significant and may lead to new therapeutic strategies." (PMID 36726797, 2023). "Further literature on the role of Bmi-1 in head and neck cancer radioresistance is limited." (PMID 36726797, 2023). "Interestingly, miRNA let‐7i was shown to be repressed by BMI1 in head and neck cancer cells." (PMID 28079973, 2017). "Interestingly, we found that BMI1 is positively involved in regulating stemness-related pathways in Head-and-neck Carcinoma, so we predicted that BMI1 may be a key downstream mRNA for circCENPM to augment the growth, metastasis, and stemness of NPC through the ceRNA mechanism." (PMID 40087716, 2025). "BMI1, ALDH1 and CD44 have been proposed as putative markers for the identification and isolation of CSCs in head and neck cancer." (PMID 28865486, 2017). "In agreement with our finding in cultured HNSCC cells that ERK3 is upregulated by BMI1, there is a positive correlation between ERK3 level and BMI1 level in the head and neck cancer tissues (correlation coefficient r = 0.432, P = 0.001)." (PMID 28079973, 2017). "Bmi1 can downregulate E-cadherin expression and induce EMT in head and neck cancer by directly binding to E-box consensus sequences in the promoter region of E-cadherin." (PMID 26023734, 2015). "Patients who were triple positive for Bmi-1, Snail, and ALDH1 were predicted to have the worst survival rate compared with other head and neck cancer patients (Bmi-1+/Snail+/ALDH1+ versus other groups)." (PMID 20936121, 2011). "Thus, further investigation into targeted therapies is necessary, but the treatment for head and neck cancers will likely entail a combination of systemic cytotoxic therapies and CSC-targeted therapies such as small molecule inhibitors of Bmi-1." (PMID 36726797, 2023). "Furthermore, according to experiments by Lobna Elkhadragy, ERK3 and BMI1 are both highly expressed in head and neck cancer and BMI1 upregulates ERK3 by suppressing the expression of Let-7i, ultimately facilitating the migration of head and neck cancer cells." (PMID 37829341, 2023). "Treatment with silibinin, a plant-based flavonoid, upregulated miR-494 in head and neck cancer, which downregulated ADAM10 (a disintegrin and metalloprotease domain 10) and BMI1 (B lymphoma Mo-MLV insertion region 1 homolog), resulting in inhibition of tumor growth and self-renewal properties." (PMID 33578944, 2021). "Taken together, our study revealed a molecular pathway consisting of BMI1, miRNA let‐7i, and ERK3, which controls the migration of head and neck cancer cells, and suggests that ERK3 kinase is a potential new therapeutic target in head and neck cancers, particularly those with BMI1 overexpression." (PMID 28079973, 2017).
head and neck cancer (continued). "To investigate whether there is a positive correlation between Bmi-1, Snail, and ALDH1 in head and neck cancers, we studied the expression of Bmi-1, Snail, and ALDH1 by immunohistochemical (IHC) staining of a panel of specimens array from 93 HNSCC patients." (PMID 20936121, 2011).
lymph node metastasis (19 papers, 2008 to 2025). "High expression of BMI1 is significantly associated with poor tumor differentiation, high clinical grade, lymph node metastasis, and poor prognosis of cervical cancer, and is an independent prognostic factor in cervical carcinoma." (PMID 33927214, 2021). "Paradoxically, high expression of BMI-1 was significantly associated with positive ER status and with the presence of lymph node metastasis in one study, indicating a diverse role of BMI-1." (PMID 18475299, 2008). "We found that significantly increased BMI1 transcripts were associated with the primary GC genotype classified as grade G3 (p = 0.011) and as lymph node metastasis N3 (p = 0.010) and counterpart marginal tissues (p = 0.026, p = 0.040, respectively) from carriers of the T/T versus C/C genotypes." (PMID 34321511, 2021). "Immunohistochemical scores for the CSC markers and BMI1 in the tumor center were compared to those obtained at the tumor invading front (n = 25) and in paired metastatic lymph node tumor islands (n = 19)." (PMID 41228340, 2025). "Instantly, lymph node metastasis, TNM stage, and worse CSS/DSS in GC patients were associated with the overexpression of Bmi-1, representing the role of Bmi-1 in the death resulted from GC." (PMID 33639931, 2021). "This suggests that the expression of BMI-1 is a reliable marker of the presence of lymph node metastases at diagnosis." (PMID 23031716, 2012). "The expression of BMI-1 in patients with laryngeal carcinoma seems to correlate with lymph node metastasis." (PMID 23031716, 2012). "Overexpression of BMI1 correlated with advanced clinical stage and lymph node metastasis; while the expression of Mel-18 negatively correlated with BMI1." (PMID 20170541, 2010). "Taken together, gastric tumor tissues expressed significantly higher BMI1 and lower Mel-18 compared with normal gastric mucosal tissues, and BMI1 correlated with lymph node metastasis, clinical stages, and prognosis." (PMID 20170541, 2010). "Notably, in GC patients, elevated Bmi-1 expression is closely correlated with unfavorable prognostic factors, including large tumor size, differentiation, invasion, lymph node metastasis, and distant metastasis." (PMID 36561502, 2022). "There was a significant positive correlation between BMI1 expression with lymph node metastasis, or clinical stage in paraffin-embedded archival gastric tumor samples as the expression of BMI1 was significantly higher in the patients with positive lymph node metastasis, or late stage disease." (PMID 20170541, 2010). "We additonally found that both Mel-18 and Bmi-1 correlated with lymph node metastasis." (PMID 21059209, 2010). "However, we did find that BMI1 overexpression positively correlated with lymph node metastasis, and clinical stages of the tumors." (PMID 20170541, 2010). "The expression of BMI1, ITGB1, and PXN-AS1 in 30 patients without lymph node metastasis was compared with 30 patients with lymph node metastasis, and only the expression of BMI1 and ITGB1 was further elevated in the tumor tissues of patients with lymph node metastasis." (PMID 38254031, 2024). "On the other hand, the BMI1 marker—which is a marker expressed under stress by quiescent cells—was found to be predominantly expressed by the SW620 cell line, derived from lymph node metastasis, which is a transitory stage for cancer cells before they colonize another organ to develop metastases." (PMID 35892561, 2022). "Furthermore, we noted that higher levels of Bmi-1 protein were correlated with a higher grade of GAC as well as unfavorable prognostic factors, including lymph node metastasis (N stage), tumor infiltration (T stage), and low differentiation." (PMID 36561502, 2022). "In more advanced tumours with higher metastatic potential, the expression of BMI‐1 was lower compared to tumours less advanced and without lymph node metastasis." (PMID 31863623, 2020).
lymph node metastasis (continued). "There was also higher incidence of Bmi-1 antibodies in sera from patients with lymph node metastasis than without lymph node metastasis." (PMID 20809956, 2010). "Bmi-1 antibodies were also significantly much prevalent in patients with lymph node metastasis than those in patients without lymph node metastasis." (PMID 20809956, 2010). "In addition, the presence of Bmi-1 autoantibodies in sera from patients with ESCC may have clinical utility in esophageal cancer screening, diagnosis and prediction of lymph node metastasis." (PMID 20809956, 2010). "Moreover, a significant positive correlation between Bmi-1 overexpression and tumor size, depth of invasion, or lymph node metastasis, and a significant negative correlation between Mel-18 low-expression with lymph node metastasis or the clinical stage were observed." (PMID 21059209, 2010).
myeloma (19 papers, 2011 to 2025). "There is a report that Bmi-1 is upregulated in multiple myeloma-associated macrophages (MM-MΦs) and that Bmi-1 modulates MM-MΦ’s pro-myeloma functions." (PMID 35897796, 2022). "BMI1, a member of a polycomb group multiprotein complex, is overexpressed in macrophages of 5T-myeloma mice compared to macrophages derived from healthy mice." (PMID 35847862, 2022). "Macrophages, isolated from myeloma bearing 5T BMI1-knock out mice showed reduced production of the pro-angiogenic factors VEGF and nitric oxide (NO)." (PMID 35847862, 2022). "The polycomb group protein BMI1 was recently shown in murine models to modulate the pro-myeloma functions of TAMs." (PMID 36428745, 2022). "Taken together with our findings that BMI1 upregulation drives MM-MΦ’s pro-myeloma functions, our work provided evidences and molecular basis that the BMI1 inhibitor targeted tumor-promoting MM-MΦs in the MM microenvironment." (PMID 33993198, 2021). "Here, we found that BMI1, a polycomb-group protein, modulates the pro-myeloma functions of MM-MΦs, which expressed higher BMI1 levels relative to normal MΦs." (PMID 33993198, 2021). "The findings of this study should provide evidences for clinical trials of BMI1 inhibitors in myeloma." (PMID 33993198, 2021). "MΦs and MM cells were subcutaneously inoculated into the mice and the pro-myeloma functions of BMI1 in MM-MΦs examined." (PMID 33993198, 2021). "In summary, we find that BMI1 is upregulated in MM-MΦs, and that BMI1 modulates MM-MΦ’s pro-myeloma functions." (PMID 33993198, 2021). "In vivo analysis showed that relative to wild-type MM-MΦs, BMI1-KO MM-MΦs lost their pro-myeloma effects." (PMID 33993198, 2021). "In future we will explore the interaction of BMI1 overexpressed MM-MΦs with immune cells in myeloma microenvironment and their effects on myeloma tumorigenesis and immune therapy efficacy." (PMID 33993198, 2021). "BMI-1 is necessary in vitro and in vivo for the clonogenic growth of myeloma cells and promotes their survival by repressing the pro-apoptotic BIM gene in some HMCL lines." (PMID 33126754, 2020). "In multiple myeloma, miR-203 is down-regulated, and its restoration suppresses BMI1 expression and inhibits myeloma cell growth." (PMID 29401683, 2018). "In support of this notion, the combination of EZH2 and BMI-1 (PRC1) inhibitors have synergistic anti-myeloma activity using HMCLs and CD138+ myeloma cells isolated from newly diagnosed or relapsed MM patients." (PMID 30761216, 2018). "Herein, we report on the anti-myeloma effects of the BMI-1 inhibitor PTC-209 and demonstrate that PTC-209 is a potent anti-myeloma agent in vitro using MM cell lines and primary MM cells." (PMID 29262596, 2017). "In line with the effect of shRNA-mediated silencing of BMI-1, we observed a significant impact on the colony formation of myeloma cells, suggesting that targeting BMI-1 also affects the viability of tumour-propagating cells." (PMID 26935956, 2016). "The polycomb complex protein BMI-1 (BMI-1) is a putative oncogene reported to be overexpressed in multiple myeloma (MM)." (PMID 26935956, 2016). "More recent results demonstrated that shRNA-mediated silencing of BMI-1 also sensitizes myeloma cells to bortezomib, which was attributed to increased expression of p21 and BCL2-associated X protein (Bax)." (PMID 26935956, 2016). "Further studies evaluating the role of BMI-1 inhibition in myeloma and the applicability of more selective inhibitors (e.g. PTC596) in vitro and in vivo are therefore warranted." (PMID 26935956, 2016). "Upregulation of BMI-1 has been reported previously in MM, and silencing of BMI-1 by small hairpin (sh) RNA significantly impaired the proliferation and colony formation of myeloma cells." (PMID 26935956, 2016). "Bmi-1 inhibitors could not only target multiple myeloma (MM) cells, but also eliminate MM-MΦs in the treatment of myeloma." (PMID 35897796, 2022).
myeloma (continued). "Taken together, these data show that BMI1 drives the pro-myeloma functions of MM-MΦs in vivo." (PMID 33993198, 2021). "Here, we find that BMI1 expression in MΦs modulates MM-MΦs’ pro-myeloma features." (PMID 33993198, 2021). "Importantly, BMI1-KO MM-MΦs lost pro-myeloma features like promoting MM growth, conferring MM drug resistance and angiogenesis in MM tumor bed." (PMID 33993198, 2021). "Overall, our data suggested that BMI1 inhibitors could not only target MM cells, but also eliminate MM-MΦs in treatment of myeloma." (PMID 33993198, 2021). "Next, we used a 5 T murine myeloma model to confirm BMI1 upregulation in MM-MΦs in vivo." (PMID 33993198, 2021). "Together, our data show that BMI1 mediates the pro-myeloma functions of MM-MΦs." (PMID 33993198, 2021). "To explore mechanisms of BMI1 upregulation in MM-MΦs, we co-cultured MM cells directly with MΦs or indirectly in trans-wells and observed BMI1 upregulation in both conditions, suggesting that BMI1 expression in MM-MΦs is modulated by myeloma-derived soluble factors." (PMID 33993198, 2021). "BMI1 is required for survival of multiple myeloma (MM) cells." (PMID 29050200, 2017). "Interestingly, a recent study of transcriptional profiling in a multiple myeloma cell line with stable knockdown of BMI1 showed that ERK3 is among the downstream target genes of BMI1." (PMID 28079973, 2017). "BMI-1 represents an attractive drug target in myeloma as well." (PMID 26935956, 2016). "Considering the negative regulation of osteoblast development by myeloma cells, blockade of BMI-1 could aggravate these effects probably leading to skeletal-related side effects." (PMID 26935956, 2016). "A similar observation was made when BMI-1-silenced myeloma cells were treated with bortezomib." (PMID 26935956, 2016). "Targeting of BMI-1 represents a promising novel therapeutic strategy among these evolving arsenals of specific inhibitors due to its universal expression pattern in MM and its impact on the myeloma microenvironment." (PMID 26935956, 2016). "It has been shown that BMI-1 is required for the clonogenic growth of multiple myeloma cells." (PMID 21851624, 2011). "Thus, our data suggest that BMI1 is needed for MM-MΦ pro-myeloma activity and that it may be a viable target for reversing MM-MΦ pro-myeloma functions." (PMID 33993198, 2021). "BMI1 inhibitors could not only target MM cells, but also eliminate MM-MΦs in treatment of myeloma." (PMID 33993198, 2021). "Thus, we hypothesized that MM-MΦ BMI1 upregulation was modulated by Hedgehog signaling via SHH secretion by myeloma cells." (PMID 33993198, 2021). "Indeed, it has been shown that BMI-1 repression sensitizes myeloma cells to bortezomib." (PMID 33126754, 2020). "This assumes that targeting Wnt signalling via BMI-1 blockade might also target myeloma cells." (PMID 26935956, 2016). "The BMI1 inhibitor PTC596 decreased tumor burden and improved the survival of mice in a murine myeloma model by depleting pro-tumor TAMs." (PMID 36428745, 2022). "In a recent paper, in mouse models, BMI1, a polycombgroup protein, showed the capability to modulate the pro-myeloma functions of TAM, which showed higher BMI1 levels compared to normal macrophages." (PMID 34298810, 2021). "Further studies examining the anti-myeloma activity of PTC-209 and more advanced BMI-1 inhibitors (e.g. PTC596) are therefore warranted." (PMID 26935956, 2016). "We find that BMI1-knockout (BMI1-KO) MΦs do not acquire pro-myeloma functions even within the MM tumor bed." (PMID 33993198, 2021). "In line with the GEP analysis and previous reports, BMI-1 gene and protein expression was observed in eight of eight human myeloma cell lines (HMCLs) tested (not shown)." (PMID 26935956, 2016).
myeloma (continued). "We confirmed overexpression of BMI-1 in CD138+ purified cells of monoclonal gammopathy of undetermined significance (MGUS), smouldering multiple myeloma (SMM), newly diagnosed and relapsed MM patients compared to healthy controls in publically available gene expression profiling (GEP) datasets." (PMID 26935956, 2016). "However, despite the identification of BMI-1 as an attractive drug target in myeloma and various other malignancies, inhibitors specifically targeting BMI-1 have not been available so far." (PMID 26935956, 2016). "Based on previous reports, inhibition of the polycomb complex protein BMI-1 might represent an attractive treatment approach for myeloma, but therapeutic agents targeting BMI-1 are not available for clinical use so far." (PMID 26935956, 2016).